HIF1A (hypoxia inducible factor 1 subunit alpha)
Diseases named in the same sentence as HIF1A in open-access papers (continued):
Sharing a sentence is not in itself a finding about the gene and the disease.
cancer (continued). "Overexpression of HIF-1α is associated with LDH-A overexpression and poor survival in many cancers." (PMID 34070746, 2021). "The overexpression of HIF-1α has been observed in many cancers, including CRC." (PMID 34059044, 2021). "HIF-1α regulates different genes to facilitate cancer metastasis." (PMID 34163032, 2021). "Hence, the co-silencing of CD73 and HIF-1α can be assumed as a novel anti-cancer treatment strategy with a high tumor suppression potential." (PMID 34502560, 2021). "Therefore, HIF-1α represents an attractive molecular target for the development of novel cancer therapeutics." (PMID 33921487, 2021). "At first, in hypoxia HIF1α induces MDR1/ABCB1 efflux transporter resulting in resistance to chemotherapeutics which are its substrates (like doxorubicin)–this mechanism is quite universal among various cancer types." (PMID 34257622, 2021). "Notably, in those cell lines expressing high amounts of PERK, we found a correlation together with Hif1a and NRF2 underlining the relevance of the PERK-NRF2-HIF-axis in human cancer." (PMID 33441543, 2021). "Additionally, SERPINB3 can protect cancer cells from oxidative stress through the up-regulation of HIF-1α transcription and HIF-2α stabilization to favor tumor growth." (PMID 33562077, 2021). "Interestingly, increased expression of PD-1L on cancer cells is thought to be mediated by a HIF-1α mechanism." (PMID 33513777, 2021). "As hypoxia and increased ROS stress frequently occur in solid tumors, ATM may promote cancer cell survival in some scenarios by stabilizing HIF1α and reducing ROS levels." (PMID 34070860, 2021). "HIF1α is the central regulator of glycolysis, cancer metabolism and cancer cell proliferation." (PMID 33730175, 2021). "Given that HIF‐1α is overexpressed in the majority of human cancers, the melatonin derivative NB‐5‐MT could represent a novel potent therapeutic agent for cancer." (PMID 33955074, 2021). "Interestingly, some of these studies report increased TRPC1 expression after hypoxia-induced EMT via HIF-1α signaling in cancer." (PMID 34936030, 2021). "Interestingly, the upstream analysis of SIRT3-modulated genes identified in our PCR array predicted the inhibition of HIF1α, further supporting the involvement of SIRT3-HIF1α-ROS connection in cancer metabolism." (PMID 33937086, 2021). "Indeed, extracellular acidosis was demonstrated to increase SOX2 expression in melanoma, confirming that SOX2 is also able to influence cancer cell metabolism profile to a more oxidative phenotype through the hypoxia-inducible factor 1-α (HIF1α) pathway." (PMID 34768751, 2021). "Abrogation of HIF1α can eliminate cancer stem cells in hematological malignancies." (PMID 33453053, 2021). "In addition to their immunosuppressive effects, volatile agents have also been shown to stimulate proliferation and migration of cancer cells in vitro, in addition to inducing HIF-1α expression, therefore promoting cancer recurrence." (PMID 34768810, 2021). "HIF-1α makes cancer cells resistant to cisplatin, oxaliplatin, and paclitaxel." (PMID 34976805, 2021). "Furthermore, PGK1 is relative with cancer cell metastatic ability because HIF-1α/PGK1 mediated epithelial-mesenchymal transition (EMT) process." (PMID 34291087, 2021). "Interestingly, hypoxia which plays a central role in the development of PE is known to induce UCA1 expression through HIF1A in both cancer cell lines and primary cultures of STB." (PMID 34055770, 2021). "Cancer cells avoid cell death because of malnutrition and hypoxia by enhancing HIF-1α expression." (PMID 34361070, 2021). "Indeed, under hypoxia or during oxidative stress, mitochondrial translocation of HIF-1α reduces mitochondrial ROS production and protects cancer cells from cell death, and possibly from irradiation-induced mitochondrial ROS production." (PMID 34539584, 2021).
cancer (continued). "Hypoxia inducible factor 1 (HIF-1), which consists of the protein subunits encoded by the two genes (HIF1A and HIF1B), is an important DNA-binding protein involved in many aspects of cancer pathogenesis including metabolic reprogramming, inflammation, angiogenesis, and resistance to therapeutics." (PMID 33815364, 2021). "It is worth mentioning that HIF-1α levels may also be increased in cancer cells through overactivation of signaling pathways (oxygen independent mechanism), including PI3K/AKT and MAPK, or through loss of VHL." (PMID 34746010, 2021). "Under hypoxic condition, cancer cells undergo adaptive changes, such as HIF‐1α activation." (PMID 33999512, 2021). "Silencing HIF-1α with RNA interference increased cancer cell chemosensitivity." (PMID 35127467, 2021). "This suggests that the post-hypoxic resistance observed in GFP+ cells might be linked to HIF-1α signaling, which we have previously demonstrated to be enriched in GFP+ cancer cells isolated from both mouse tumors and lungs." (PMID 34771673, 2021). "MTOR regulates cancer cell metabolism by controlling expression of the TFs c‐Myc and HIF1α." (PMID 34003553, 2021). "HIF1A activity is under epigenetic control in human cancer cells and hematopoietic cell lines." (PMID 34262470, 2021). "In addition, Nrf2 induces angiogenesis through stimulating hypoxia-inducible factor 1-alpha (HIF-1α)-dependent vascular endothelial growth factor (VEGF) expression in cancer cells and promoting cancer growth." (PMID 34070502, 2021). "This group also showed that LETM1 may be a marker of CSCs in this cancer; expression of this protein positively correlated with that of the stemness marker OCT4 as well as cyclin D1, and was associated with hypoxia-inducible factor 1 alpha (HIF-1a) expression." (PMID 33799834, 2021). "Therefore, HIF-1α is becoming an increasingly attractive therapeutic target in the treatment of cancer." (PMID 33996598, 2021). "Additionally, it is worthy of note that HIF-1α and c-myc have been reported to serve as dominant regulators of glycolysis by targeting multiple glycolysis-related genes in a variety of cancers." (PMID 35096814, 2021). "Furthermore, HIF-1α can be activated by a number of cancer cell signaling pathways and plays a crucial role in the carcinogenesis process." (PMID 34926261, 2021). "One such activator is hypoxia inducible factor alpha (HIF1α), which is known to trigger the transcription of genes involved in angiogenesis, erythropoiesis, proliferation, glycolysis, and other processes essential for survival of cancer cells." (PMID 33546324, 2021). "The hypoxic environment present in solid tumors is not the only cause of HIF-1α over-expression in cancer cells." (PMID 34141616, 2021). "Moreover, SPRY4-IT1 was found to bind STAU1, promote STAU1 recruitment to the 3′-UTR of TCEB1 mRNA, and affect TCEB1 mRNA stability and expression, resulting in hypoxia-inducible factor 1α (HIF-1α) upregulation, and thereby affecting cancer cell metastasis." (PMID 34163032, 2021). "Furthermore, TGF-β is involved in multiple signaling pathways regulated by redox homeostasis in cancer, through the regulation of redox-sensitive transcription factors, such as NF-kB and HIF-1α." (PMID 34205678, 2021). "Moreover, the importance of HIF-1α in Ras/MAPK signaling was previously noted for Her2 positive cancers, which require HIF-1α for anchorage independent growth." (PMID 33672199, 2021). "Overexpression of HIF1α is observed in a variety of cancers." (PMID 34686682, 2021). "Remarkably, both the 67 NPM1/HIF‐1α‐dependent gene signature gene and the hypoxic gene signatures were associated with poor prognostic outcome in the cohort of patients with DLBC, GBM, or THYM cancer types." (PMID 34388291, 2021). "Thus, a decrease in HIF-1α expression was observed to downregulate the mRNA expression of hypoxia response genes in the current study, suggesting that cancer malignancy can be directly decreased." (PMID 33806179, 2021).
cancer (continued). "Finally, IGF1R and HIF1A genes enriched in Cancer pathways were closely related to the occurrence and development of HBV-related HCC." (PMID 33863948, 2021). "In the microenvironment of oxygen-glucose shortage, HIF1A is a major factor in cancer survival." (PMID 34132347, 2021). "Ref-1’s regulation of HIF-1α along with other TFs may contribute to the metabolic rewiring that is observed in many cancers." (PMID 34376225, 2021). "HIF-1α transactivates genes whose protein products are involved in many aspects of cancer biology, including cell immortalization and proliferation, maintenance of stem cells, genetic instability, energy metabolism, angiogenesis, EMT, cancer cell invasion and metastasis, and chemotherapy resistance." (PMID 34681797, 2021). "However, hypoxia and HIF-1α activation were also shown involved in pathological mechanism and have been particularly studied in the cancer field." (PMID 34281273, 2021). "PPAR-α agonists diminished hypoxia-induced HIF-1α expression and activity in cancer cells." (PMID 34268320, 2021). "Moreover, elevated levels of reactive oxygen species (ROS) can activate mtOXPHOS, and thereby increase hypoxia-inducible factor-1alpha (HIF-1α) expression to maintain the status of stem cell-like cancer cells." (PMID 33628590, 2021). "However, there are few researches exploring the relationship between cancers and HIF1α in the veterinary field." (PMID 34124226, 2021). "Targeting HIF-1α and hypoxia-related effector molecules could impair cancer cell survival by attenuating glucose metabolic processes or inhibiting VEGF-induced angiogenesis and survival-promoting signaling pathways." (PMID 33401572, 2021). "Although glycolysis, HIF-1α and genomic instability are linked to cancer and invasiveness, we did not observe transformation of the HFF-shCOX4I1 or patient cells." (PMID 33672589, 2021). "Many studies have reported that hypoxia, as a signal for the molecular clock, disturbs the normal circadian rhythm in cancer, and there is a bidirectional relationship between the HIF‐1α signaling pathway and the core clock genes that control the circadian rhythm." (PMID 33955074, 2021). "RSV treatment reduced HIF-1α in cancer cells in vitro, which might explain the reduction in the CD73 activity observed in RSV-treated cells in our study." (PMID 34539333, 2021). "Furthermore, this reveals a clear cellular role for HIF1A under normoxia, likely explained by the existence of additional HIF1A-activating stimuli such as growth factor signaling and genetic alterations in cancer cells." (PMID 33654095, 2021). "Based on these, we speculated that the 4-MTBITC modulate DMBA induced glycolytic pathway and hypoxia pathway by downregulating the expression of HIF-1α and mTOR along with some amino acids that are needed for cancer growth." (PMID 34447314, 2021). "Moreover, HIF-1α signaling can lead to damage to antigen presentation and resistance of cancer cells to T cell-mediated cytotoxicity." (PMID 34887404, 2021). "HIF-1α protein levels were also reduced in the cancer cells with miR-7641 overexpression." (PMID 34238918, 2021). "Therefore, HIF-1α is considered to be a potential prognostic marker of many cancers, including OSCC." (PMID 34465721, 2021). "The increased HIF-1α correlates with cancer progression and could serve as a potential therapeutic target in cancer patients." (PMID 33750303, 2021). "Interestingly, mutations that cause either oncogene activation or tumor suppressor inactivation can increase HIF-1α expression in cancer cells." (PMID 34639215, 2021). "This hypoxic cancer-stromal crosstalk might be mediated by HIF-1α and enhances the invasive features of PC." (PMID 33436044, 2021). "It is important to note that phosphorylation of AKT may lead to upregulation of HIF-1α expression and translocate to the nucleus in cancer cells." (PMID 34257808, 2021).
cancer (continued). "Hence, this study further opens a new dimension to the role of viruses in replication and proliferation of other cancer types where HIF1α expression is induced in infected cells." (PMID 34279223, 2021). "Baicalein can inhibit the function of HIF‐1α in several types of cancer cells." (PMID 34841716, 2021). "Indeed, the induction of PRODH activity in cancer cells destabilizes HIF1α and down-regulates the transcription of HIF1α target genes." (PMID 34458276, 2021). "HIF-1α is a key transcriptional factor in cancers which can be regulated by miR-138 and -210." (PMID 33919449, 2021). "KLF4 is able to induce pluripotent stem cells and HIF-1α reportedly induces its expression in cancer cells, suggesting that hypoperfusion might be involved in KLF4 expression in the AAA wall." (PMID 33672844, 2021). "SIRT3 promotes cancer cell apoptosis through destabilizing HIF1α." (PMID 34795840, 2021). "could show that knockdown of HIF-1α leads to an increased response on radiotherapy in human cancer cell models." (PMID 33856525, 2021). "While HIF-1A expression in cancer has been studied in the context of its metabolism and hypoxia, here, we found that matrix stiffness could also modulate its expression independently from the oxygen availability." (PMID 34209094, 2021). "Hypoxia/HIF1α is shown to regulate cancer stem cell-like features." (PMID 34686682, 2021). "Therefore, to investigate the mechanism of inflammation-induced TIC generation and treatment of cancer induced by chronic inflammation, it is important to determine the molecular mechanism of HIF-1α induction in response to MYD88 signals in more detail." (PMID 33597599, 2021). "Thus, we tested the effect of CDK4/6/HSP90 dual targeting on HIF1α expression in various cancer cell lines." (PMID 34686682, 2021). "The induction of quiescence by HIF-1α may appear to contradict some evidence from its role in cancer growth." (PMID 33472628, 2021). "Due to the involvement of HIF1α in multiple aspects in cancer biology, whether the combination treatment affects other HIF1α-mediated cancer phenotypes remains to be tested." (PMID 34686682, 2021). "Moreover, MCT4 is the only monocarboxylate transporter through which expression is modulated (via HIF-1α) by a hypoxic environment, a feature characteristic of malignant tumors." (PMID 34357326, 2021). "It has been shown that HIF-1α requires pyruvate for cancer cells under aerobic conditions." (PMID 33718357, 2021). "This article reviews the anti-cancer effect of phytochemicals in connection with HIF-1α regulation." (PMID 34575983, 2021). "HIF-1α is a crucial regulator of metabolism and a well-characterized oncoprotein in cancer cells." (PMID 34976998, 2021). "Indeed, studies have shown that HIF-1α and VEGF overexpression are associated with cancer aggressiveness and poor overall survival of cancer patients." (PMID 34829672, 2021). "The results indicated that these TFs—HIF1A, JUN, LEF1, and FOS—were negatively correlated with four glycolysis-associated lncRNAs across the five cancer types, suggesting that the low expression of these lncRNA signatures was accompanied by glycolytic signaling and oncogenic TF activation." (PMID 33627136, 2021). "Some studies also proved that the overexpression of ALDOA might contribute to tumorigenesis and the progression of cancers through modulation of HIF-1α signaling." (PMID 33858449, 2021). "LPA upregulated HIF-1α expression in the tested cancer cells." (PMID 34065317, 2021). "Moreover, a publication of interest has highlighted a surprising correlation between the plasma membrane fluidity of carcinoma cells with HIF1-α and VEGF rates." (PMID 33747916, 2021). "The upregulation of SIRT3 due to UPRmt elevates the ROS production and stabilization of HIF-1α, which initiates the switching of the anaerobic glycolytic process, the Warburg effect in various carcinomas, including breast cancer, hepatic, gastric, and colorectal carcinoma." (PMID 34717757, 2021).
cancer (continued). "Studies report the role of HIF-1α in HK2 expression, e.g., inhibition of HK2 resensitizes tamoxifen-resistant cells and HIF-1α, a transcription factor associated with hypoxia, is linked to cancer initiation." (PMID 32806533, 2020). "However, the inhibition of TFAP2A SUMOylation under hypoxic condition can improve the transcriptional activity of HIF-1α and promote cancer cell survival." (PMID 33273928, 2020). "Increased glucose consumption by cancer cells produces high levels of lactic acid, which is expelled into the extracellular fluid through proton-linked monocarboxylate transporters (MCT4), also upregulated by HIF-1α." (PMID 32824207, 2020). "Moreover, JMJD2C has also been shown to serve as a co-activator for hypoxia-inducible factor 1 (HIF1α) for cancer progression." (PMID 32972441, 2020). "Several HIF-1α inhibitors, which have different inhibitory mechanisms, including transcriptional and post-transcriptional modulations, have demonstrated successful suppression of cancer cell growth." (PMID 32847004, 2020). "HIF-1α can be stabilised independently of hypoxia by the increased expression of growth factor receptors and the dysregulation of oncogenes, such as the amplification of c-myc in cancer cells, and by intracellular lactate accumulation." (PMID 36046070, 2020). "Although major insights have come from research on mouse models, there are overwhelming data on the increased stability of HIF-1α or HIF-2α expression in human cancer, promoting progression and worsening prognosis in human solid cancers such as breast, prostate, and colorectal cancer." (PMID 32579052, 2020). "As HIF-1α is related to M2 macrophage polarization in cancer, we speculated whether HIF-1α can influence the progression of gastric lesions by regulating gastric macrophage polarization." (PMID 33376580, 2020). "Continuing evidence indicates that both HIF-1α and ncRNAs play essential roles in human cancers." (PMID 32014012, 2020). "Thus, the availability of various inhibitors suggests that it is possible to disrupt Nrf2 as well as HIF1α pathway for preventive gain of the human cancers resulted from environmental or occupational iAs exposure." (PMID 32226544, 2020). "In a series of researches based on cancer cell lines, βig-h3 is found to have a strong functional interaction with hypoxia-inducible factor-1 a (Hif-1a), a key pro-chondrogenic factor that directs the differentiation to chondrocytes in hypoxic microenvironment." (PMID 32312943, 2020). "HIF-1α is often regulated through several oncogenic cellular molecules like the Akt/mammalian target of rapamycin (mTOR), which is found to be upregulated in cancer." (PMID 33014057, 2020). "Selectively increased HIF-1α expression in Treg cells could therefore be considered a therapeutic approach to treating cancer because it would destabilize Treg cells and convert them into inflammatory T cells." (PMID 33024109, 2020). "This link between HIF-3 and lipid metabolism may also explain why only a few cancer cell lines express the long HIF3A splice variants, whereas the HIF-1α that drives glucose metabolism is their major HIF form." (PMID 31768607, 2020). "Recent advances in cancer biology at the cellular and molecular levels highlighted the HIF-1α pathway as a crucial survival pathway for which novel strategies of cancer therapy could be developed." (PMID 31947661, 2020). "The authors demonstrated that LW1564 could limit HIF-1α accumulation and inhibit the proliferation of various cancer cell lines." (PMID 33235318, 2020). "It was also observed in cancer cells that TGase 2 was induced by HIF-1α under hypoxia." (PMID 32260198, 2020).